RELT (RELT TNF receptor)
Diseases named in the same sentence as RELT in open-access papers (continued):
Sharing a sentence is not in itself a finding about the gene and the disease.
tumor (12 papers, 2011 to 2025). "In this study, we determined that high expression of RELT in ccRCC predicts its poor prognosis and is strongly associated with the tumor immune microenvironment." (PMID 41376629, 2025). "RELT promotes the development of ccRCC and may play a role in regulating the tumor immune microenvironment, which affects the prognosis of ccRCC patients, and RELT may become a new biomarker associated with immune infiltration in ccRCC." (PMID 41376629, 2025). "According to the whole-cancer analysis of the TCGA database, RELT expression was higher in tumor tissues than in adjacent tissues in 16 types of cancer." (PMID 41376629, 2025). "Our in vitro experiments co-cultured tumor cells with T cells, demonstrating that RELT knockdown significantly enhanced T cell-mediated killing of ccRCC cells, leading to increased apoptosis." (PMID 41376629, 2025). "This implies that higher RELT expression and lower tumor purity in ccRCC predict a poorer prognosis and a higher likelihood of recurrence in ccRCC patients." (PMID 41376629, 2025). "We found that RELT showed dark brown IHC staining in tumor tissues, indicating that its expression was significantly higher in tumor tissues than in normal tissues." (PMID 41376629, 2025). "Following co-culture of the 786O-shRELT, 786O-shCtrl, 769P-shRELT, and 769P-shCtrl cell lines with T cells, we detected increased apoptosis in tumor cells following RELT knockdown." (PMID 41376629, 2025). "We carried out an analysis of the role of RELT in the ccRCC tumor immune microenvironment based on multiple algorithms." (PMID 41376629, 2025). "Genetic techniques used to study immune infiltration had to take into account the purity of tumor cells in clinical cancer samples and the expression of RELT versus ccRCC (r=-0.321, p<0.001) purity." (PMID 41376629, 2025). "Immunoscore as well as tumor purity analyses based on data from the TCGA database found that RELT was positively correlated with both StromalScore, ImmuneScore, and ESTIMATEScore in multiple cancers." (PMID 41376629, 2025). "These sites were annotated to genes involved in diverse biological pathways, including neurological development (AHNAK, PGAP3), lymphocytic function (ITGAL), apoptosis (RELT), tumor suppression (ZGPAT), and endothelial-to-mesenchymal transition (PRSS23)." (PMID 32084330, 2020). "Keywords include ccRCC, RELT, tumor immune microenvironment, JAK/STAT pathway, and macrophage." (PMID 41376629, 2025). "Immune infiltration analysis showed that RELT was significantly associated with immune cells such as B Cells, CD8+ T Cells, CD4+ T Cells, and Macrophages and may affect the tumor immune microenvironment of ccRCC by influencing macrophages." (PMID 41376629, 2025). "Therefore, inhibiting RELT expression in T cells is an avenue worth exploring to potentially increase the effectiveness of adoptive cell therapy for tumor patients." (PMID 37893069, 2023). "Consequently, OXSR1-mediated activation of RELT should be considered an important mechanism for the apoptosis induction and tumour development inhibition." (PMID 34072756, 2021). "This means that high RELT expression is often accompanied by high levels of immune cell infiltration, stromal cell infiltration, and lower tumor purity, which implies that ccRCC patients with high RELT expression may have shorter OS and faster recurrence rates." (PMID 41376629, 2025). "First, we analyzed the tumor and adjacent tissues of ccRCC patients from the TCGA database and identified 3,114 differentially expressed genes, of which 1,536 genes were highly expressed in tumors, 1,571 genes were lowly expressed, and RELT was included in the high-expression group." (PMID 41376629, 2025). "The relationship between RELT and cancer may be another example of a protein that can either promote apoptosis or pro-tumorigenic functions, similar to the ability of TNFα treatment to induce either apoptosis or promote tumor growth in TNBC." (PMID 39767574, 2024).
tumor (continued). "Similarly, RELT+/+ CD8+ T cells exhibited increased tumor antigen-specific activation and tumor growth suppression when transferred into RELT−/− mice versus RELT+/+ mice, suggesting that expression of RELT in additional cells besides CD8+ T cells also function to inhibit CD8+ T cell activation." (PMID 37893069, 2023). "Given that MHC class I serves as the receptor of HA-2, the interaction between RELT and MYO1G identified in our study suggests a potential mechanism by which tumor cells can evade immune recognition by CD8 + T cells upon cetuximab therapy." (PMID 38168324, 2023). "Therefore, we speculated that RELT might play a role in tumor immunosuppression in PCa." (PMID 34804963, 2021). "RELT and TNFSF10 had high expression levels in tumor tissues compared with normal tissues, while EDA2R and TNFSF18 had low expression levels in tumor tissues compared with normal tissues in TCGA dataset." (PMID 34484286, 2021). "First the prominent phenotype of mice lacking RELT was enhanced T-cell responses, including increased killing of tumor cells by CTLs, indicating that RELT suppresses T-cells." (PMID 39767574, 2024). "The activation of myeloid-derived suppressor cells (MDSCs) in response to tumor growth was also reduced in mice lacking RELT, supportive of a model in which RELT suppresses immune responses against tumors." (PMID 37893069, 2023). "In addition, paired sample analysis was conducted, revealing that RELT expression in ccRCC tumor samples was higher than in adjacent non-tumor samples (P<0.001)." (PMID 41376629, 2025). "Mice lacking RELT exhibit enhanced populations of CD4+ T cells, and enhanced CD8+ T cell responses to tumor cells, indicating that RELT likely functions in part by suppressing T cell responses." (PMID 37893069, 2023).
cancer (4 papers, 2019 to 2025). A tumor composed of atypical neoplastic, often pleomorphic cells that invade other tissues. "RELT is able to activate the NF-κB pathway, which promotes cancer progression and is associated with activation of the p38 and JNK MAPK pathways." (PMID 41376629, 2025). "Several studies have shown that aberrant expression of RELT is associated with immune escape from cancer, including ESCC and PRAD." (PMID 41376629, 2025). "First, the ssGSEA algorithm was applied to analyze the correlation between RELT expression and immune cells, and it was found that RELT expression was positively correlated with a variety of immune cells in pan-cellular carcinomas." (PMID 41376629, 2025). "We sought to further explore the relationship between RELT and cancer by examining the expression of RELT family members in various cancer cell lines using Western blotting." (PMID 39767574, 2024). "RELT (Receptor Expressed in Lymphoid Tissues), also known as TNFRSF19L, is a TNFRSF member implicated as an important regulator of the immune system and is associated with several cancers." (PMID 39767574, 2024). "Patients in the cohort with higher expression of RELT were more likely to have cancers with an immunosuppressive environment, in addition to a higher mutation frequency, higher incidence of metastasis to lymph nodes, and worse prognosis." (PMID 37893069, 2023). "However, RELT may function in a pro-tumorigenic mechanism depending on the type of cancer, as RELT functions as an oncogene in ESCC and potentially in other cancers." (PMID 39767574, 2024). "Additionally, multiple lines of evidence indicate that RELT may promote an immunosuppressive environment in cancer." (PMID 39767574, 2024). "In order to analyze the correlation between RELT expression and immune cell infiltration in ccRCC, we applied various algorithms such as ssGSEA, CIBERSORT, EPIC, TIMER, and xCell in pan-cancer." (PMID 41376629, 2025). "Surprisingly, RELT exhibited much stronger protein expression in cell lines representing either breast (MDA-MB-231 and MCF7) or lung (H358) cancer in comparison to cell lines of hematopoietic origin." (PMID 39767574, 2024).
RELT also shares sentences with these, for which no sentence is quoted: renal cell carcinoma (2 papers); breast tumor (1); brucellosis (1); colon cancer (1); COVID-19 (1); E. coli infection (1); hepatocellular carcinoma (1); Hypertension (1); infection (1); lung adenocarcinoma (1); myocardial infarction (1); osteosarcoma (1); periodontitis (1); prostatic adenocarcinoma (1); rhabdomyosarcoma (1); tuberculosis (1); vasculitis (1).